HGF (hepatocyte growth factor)
Diseases named in the same sentence as HGF in open-access papers (continued):
Sharing a sentence is not in itself a finding about the gene and the disease.
tumor (continued). "Such a paracrine loop, mediated by the cancer-derived HGF-inducers and stroma-secreted HGF, confers a key mechanism of tumor metastasis." (PMID 23296269, 2013). "Hepatocyte growth factor (HGF) is a multifunctional cytokine produced by tumour cells and myofibroblasts in tumour stroma." (PMID 24137336, 2013). "The majority of TGFβ1 and HGF expression was localised in the cytoplasm of tumour and dysplasia cells, and positive cells were distributed in the proliferative basal cell zone." (PMID 24137336, 2013). "Here, we report the finding that treatment with EGFR inhibitors of various tumor cells, when stimulated with hepatocyte growth factor (HGF) and EGF, results in transient upregulation of phosphorylated AKT." (PMID 23812422, 2013). "Particularly, both tumor and mesenchymal cells can be responsible for increased HGF production, leading to paracrine and/or autocrine mechanisms for receptor activation." (PMID 24378750, 2013). "We want to develop a serial of methods to apply anti-c-Met antibodies in the clinic tumor therapy, for example, developing antibodies that can block the HGF/c-Met pathway, conjugating antibodies with immunotoxins, radioimmunoconjugates and chemotherapy drugs." (PMID 23675455, 2013). "Transgenic animals producing human HGF are reported to show that c-Met is involved in in vivo tumor growth." (PMID 23762292, 2013). "Recently, NRP-1 was found to promote tumor progression by interacting with other proteins, such as integrin beta-1 and hepatocyte growth factor/scatter factor." (PMID 23251257, 2013). "MET decoy receptors are soluble forms of the cMET extracellular domain which compete with HGF and inhibit cMET dimerization; in vitro and in vivo mice models demonstrate suppression of HGF-induced tumor cell migration and metastasis." (PMID 23606971, 2013). "Antibody stability in vivo and their ability to recruit the host immune system to destroy tumour cells make this form of therapy clinically advantageous over other types of c-Met/HGF inhibitors." (PMID 23859937, 2013). "In the tumor microenvironment, HGF regulates the expression of c-Met and CXCR4 through autocrine or paracrine actions." (PMID 22242160, 2012). "In order to mimic EGFR/Met crosstalk in the tumor microenvironment we used conditioned media from HGF-producing fibroblasts as well as co-cultures of TNBCs with these fibroblasts, and again demonstrated that the activation of Met mediated EGFR TKI resistance." (PMID 22788954, 2012). "They used a reversephase protein array to identify that stromal cells secrete hepatocyte growth factor(HGF) that confers tumor cell resistance to RAF inhibitors (e.g., vemurafenib)." (PMID 23336100, 2012). "Expression of HGF, the ligand for Met, is limited to cells of mesenchymal origin, suggesting that communication between the tumor and the stroma is required for Met activation." (PMID 22788954, 2012). "Several studies have also pointed out the importance of the paracrine action of HGF on neoplastic transformation in several tumor types, such as in the Epithelial Cell Ovarian Carcinoma (ECOC)." (PMID 22999213, 2012). "c-met, the receptor of HGF, is expressed by diverse tumor cells, but can also be present at the surface of immune cells such as DC." (PMID 23320019, 2012). "Among others PI3K signaling is activated by the hepatocyte growth factor (HGF) that regulates proliferation of hepatocytes during liver regeneration but also fosters tumor cell proliferation." (PMID 23226133, 2012). "The HGF/c-Met pathway is an important regulator of tumor invasion and metastasis in various types of human cancer." (PMID 22962849, 2012). "This is consistent with the previous studies demonstrating the role of PKC-ERK cascade in mediating cell migration of a lot of tumor cells induced by metastatic factors including HGF." (PMID 23028692, 2012). "HGF induction is observed in injured skeletal muscle and myocardium and in many tumors and tumor-derived cell lines along with its receptor – c-met." (PMID 22719942, 2012).
tumor (continued). "Concordantly, the activation of HGF/c-Met signaling positively correlates with tumor metastasis in HCC." (PMID 22912725, 2012). "We found that in presence of this Met TKi, HGF lost its capacity to recover ErbB2 tumor cells from EGFR inactivation (A+P+H)." (PMID 23028720, 2012). "Recently, it has been shown that innate resistance to vemurafenib can be attributed to the secretion of hepatocyte growth factor (HGF) by the tumor micro-environment." (PMID 23372575, 2012). "The fact that tumor cells respond to HGF with increased proliferation and survival following EGFR inhibition has also been addressed in non-small cell lung cancer (NSCLC)." (PMID 23028720, 2012). "MET tyrosine kinase and its ligand, hepatocyte growth factor (HGF), play a pivotal role in the activties of tumor cells." (PMID 23554766, 2012). "The mean wet lung weight in HGF-injected tumor-bearing mice was greater as compared with those injected with PBS or PKCζ-shRNA." (PMID 22242160, 2012). "On the other hand, tumor stroma-derived HGF plays a central role in the invasion of cancer cells in growing tumors." (PMID 22536224, 2012). "The tumor-derived HGF expression, cell proliferation index (PI) and intratumoral microvessels were evaluated by immunohistochemistry." (PMID 22741575, 2012). "The tumor-derived HGF mRNA and protein expressions were significantly decreased in vitro after transfection of HGF siRNA." (PMID 22741575, 2012). "In some cases, tumor cells express both HGF and c-Met, thus potentially establishing an autocrine loop in which the secreted HGF ligand by tumor cells binds to the c-Met receptor and causes its activation." (PMID 22639908, 2012). "Treatment of U87MG GBM xenografts with Rilotumumab, a fully human neutralizing antibody directed to HGF/SF, significantly inhibited tumor growth in mouse xenograft models." (PMID 22511956, 2012). "Changes in the MET gene involve ligand-independent activation of the intracytoplasmic tyrosine kinase domain leading to activation of the hepatocyte growth factor (HGF)/MET pathway resulting in tumor formation." (PMID 22312516, 2011). "Analysis of total beta-catenin and Y654-beta-catenin in response to HGF activation in the cell lines, mirrors that observed in our HB tumour cohort." (PMID 21992464, 2011). "Activated myofibroblasts in the tumor microenvironment were responsible for c-Met activation through production of hepatocyte growth factor (HGF)." (PMID 20981352, 2011). "Hypoxia has also been shown to increase the expression of c-Met, leading to increased sensitivity to HGF and an invasive phenotype in the tumor cells." (PMID 21915264, 2011). "For example, a HGF-independent activation of c-Met by fibronectin was reported to promote the tumor invasion/metastasis." (PMID 21496277, 2011). "The expression of c-MET and HGF is associated with tumor progression and a number of clinical studies have implicated the prognostic and predictive value of c-MET and/or HGF measurements." (PMID 21283737, 2011). "We measured HGF/c-MET ligand-receptor complexes in the same NSCLC carcinoma tumor panel that was used for individual c-MET and HGF measurements." (PMID 21283737, 2011). "To address this unmet need, we applied our antibody proximity technology to the development of a quantitative assay that measures HGF expression levels in FFPE tumor specimens." (PMID 21283737, 2011). "Ectopic expression of HGF in breast fibroblasts was used to promote tumor initiation and growth of human breast epithelial organoids in the humanized fat pads of NOD/SCID mice." (PMID 21249190, 2011). "The crosstalk between tumor cells and stromal cells is bi-directional, with hepatocyte growth factor and stromal cell-derived factor-1 secreted by CAFs, stimulating the growth and progression of tumor cells themselves." (PMID 24213136, 2011). "Tumor cells producing high levels of HGF can activate c-met by either autocrine or paracrine signaling mechanisms, which leads to Stat3 activation and gene transcription." (PMID 21595927, 2011).
tumor (continued). "We utilized the same NSCLC tumor panel that was used for the evaluation of the c-MET proximity assay to evaluate the HGF proximity assay." (PMID 21283737, 2011). "Deprivation of HGF by neutralizing with anti-HGF antibodies diminished the tumor promoting activity of CAFs." (PMID 21249190, 2011). "The hepatocyte growth factor (HGF)/c-Met signalling cascade is considered to be widely involved in the tumour metastatic process." (PMID 21102580, 2011). "The results reflected those seen in HB tumours with c-Met activated β-catenin found only in the cell line with wild type CTNNB1 following HGF treatment." (PMID 21992464, 2011). "HGF appears to play a significant role in tumor angiogenesis by stimulating endothelial cell migration, proliferation, and capillary tube formation." (PMID 21941412, 2011). "To investigate the possibility of Wnt-independent activation of β-catenin, we analysed our tumour cohort for possible HGF/c-Met related tyrosine phosphorylation of β-catenin." (PMID 21992464, 2011). "We confirm for the first time that interference with the HGF/c-met/Stat3 signaling pathway can block tumor cell invasion in an in vivo model, and we present evidence for a positive feedback loop between Stat3 and c-met." (PMID 21595927, 2011). "This stresses the importance of HGF paracrine/endocrine function in MET mutant tumours that is involved in angiogenesis, growth, migration and invasion and the potential role of MET inhibitors in cases with MET mutations." (PMID 21847116, 2011). "Another c-Met inhibitor, SGX523, also had better anti-tumor effects when combined with erlotinib in an HGF overexpressing scid mouse model." (PMID 21390244, 2010). "In our study, we found that expression of HGF in tumor tissues after incomplete RFA was much higher than that in tumor tissues without RFA." (PMID 20667141, 2010). "Here we describe a preclinical model in which Met and/or HGF/SF inhibition can be assessed in multiple tumor types." (PMID 21049054, 2010). "In the present study, it was shown that expression of PCNA, MMP-9, VEGF, HGF and IL-6 in tumor tissues in groups I, II and III, which received incomplete RFA, increased remarkably." (PMID 20667141, 2010). "Mean tumor number in the group using both the HGF neutralizing antibody L2G7 and the EGFR inhibitor gefitinib was significantly lower than with single agents." (PMID 21390244, 2010). "Tumour necrosis factor-α-mediated signalling maintains tumour neovascularisation partly by inducing hepatocyte growth factor (HGF) to support lung metastasis." (PMID 20087353, 2010). "Stellate cells and myofibroblasts are induced to secrete HGF by tumor cell products and HGF stimulates tumor cell invasiveness in turn." (PMID 24281095, 2010). "One of the key components in EMT-dependent tumor proliferation, cell motility and invasion signaling is the hepatocyte growth factor (HGF) receptor, also referred to as c-Met." (PMID 20828379, 2010). "HGF/c-Met signaling is activated in angiogenesis and tumor growth, therefore, several strategies have been explored for inhibiting this pathway." (PMID 20667141, 2010). "Expression of HGF and IL-6 in the tumor tissues of group I increased dramatically in comparison with that in the control group." (PMID 20667141, 2010). "Expression of PCNA, MMP-9, VEGF, HGF and IL-6 in tumor tissues increased significantly in the RFA-treated groups compared with the control group, and of the increases were greatest in the 55°C group (P < 0.05)." (PMID 20667141, 2010). "The invasive and metastatic behaviour of tumour cells is regulated by extracellular growth factors like hepatocyte growth factor (HGF), which is a ligand for the c-Met receptor tyrosine kinase." (PMID 21172020, 2010). "The fourth and final characteristic that defines a TAF is secretion of tumor-supportive growth factors, including HGF, EGF and IL6." (PMID 19352430, 2009).
tumor (continued). "Several adenocarcinoma tumor-microenvironment crosstalk models implicate growth factors including HGF, VEGF, TGF-β, and FGF in the promotion/progression of tumorigenesis." (PMID 19352430, 2009). "Nk4 (also known as Interleukin (IL)32b) is a competitive antagonist of the HGF c-Met system and inhibits c-Met signalling and tumour metastasis." (PMID 19272140, 2009). "To examine the effects of HGF/c-Met-mediated uPA induction on the invasive properties of tumor cell phenotypes, we performed an in vitro invasion assay using a matrigal migration chamber." (PMID 19497102, 2009). "The HGF/c-Met interaction plays a pivotal role in cancer invasion that is mediated by the tumor stromal cell production of HGF, which can induce ECM degradation, tubule formation and angiogenesis." (PMID 19352430, 2009). "In vitro, PHA665752 inhibits constitutive and HGF/SF-stimulated c-Met phosphorylation, cell growth, motility, and migration of different tumor cell lines." (PMID 19939254, 2009). "Hepatocyte growth factor (HGF) has been shown to stimulate the invasion, metastasis and migration in a variety of tumor cells." (PMID 19471205, 2009). "We also report the effect of augmented PTEN expression on PHA665752-mediated inhibition of c-Met-HGF/SF signaling in this tumor." (PMID 19939254, 2009). "VEGF is a potent angiogenic factor, while growth factors such as bFGF, EGF, and HGF can stimulate proliferation of not only tumor cells but also endothelial cells and thus manifest proangiogenic and antiapoptotic effects." (PMID 18728788, 2008). "HGF is well known for its ability to protect tumor cell death triggered by various DNA-damaging stimuli including gamma-radiation and chemotherapeutic agents." (PMID 18992144, 2008). "The multifunctional effects of HGF:c-Met signaling in tumor cells are mediated by a network of signal transduction pathways including mitogen-activated protein kinase (MAPK) and phosphoinositide 3-kinase (PI3K)." (PMID 18992144, 2008). "Hepatocyte growth factor (HGF) is a multifunctional cytokine produced by cells of the supportive tumour microenvironment, and a central regulator of the invasive/metastatic phenotype of neoplastic cells." (PMID 18941460, 2008). "The use of PS/PSN antiangiogenic drugs for the treatment of cancer has some advantages: AGFs such as FGFs and hepatocyte growth factor (HGF) act as pleiotropic cytokines that, in addition to neovascularization, induce proliferation of tumor cells." (PMID 19002078, 2008). "Hepatocyte growth factor/scatter factor (HGF), a cytokine that stimulates tumor cell motility, invasion and angiogenesis, was overexpressed in all the four treatment groups." (PMID 18549507, 2008). "Studies with orthotopic GBM mouse models have shown that imaging reagents can leak from the intracranial tumors, indicating that the BBB is compromised and anti-HGF mAbs, despite their large molecular size can inhibit orthotopic tumor growth in the brain." (PMID 19055779, 2008). "Chemokines and growth factors, such as HGF, seem to act as mediators between the tumour microenvironment and the neoplastic cells, and are important in tumour progression and metastasis." (PMID 18941460, 2008). "The JNK (c-jun NH2-terminal kinase), a well known cell death promoting signaling pathway, was found to be activated by HGF and to mediate HGF-induced cell death in other tumor models." (PMID 18992144, 2008). "This positive contribution of a Sulf to Wnt-dependent tumor growth is in striking contrast to several reports in which the enforced expression of Sulfs antagonizes other signaling pathways (e.g. FGF-2, and HGF) in tumor cells and suppresses cell growth." (PMID 17460759, 2007). "Over-expression of c-Met expression enhanced the expression of angiogenesis factors IL8, VEGF, and PDGF in response to HGF in vitro, and increased tumorigenesis and metastasis in the tumor microenvironment." (PMID 17498291, 2007).
tumor (continued). "Hepatocyte growth factor was immunostained extensively in 100% of all the tumour tissues examined, and there was intratumoural staining as well." (PMID 17667909, 2007). "We have also examined in details the topographic distribution of the various phosphoproteins in the c-MET/HGF pathway in SCLC tumour tissue." (PMID 17667909, 2007). "We also studied the role of c-MET/HGF signalling pathway in SCLC tumour tissues using phosphospecific antibodies IHC analysis with focus on its topographic pattern of expression." (PMID 17667909, 2007). "HGF promoted expression of angiogenesis factors in tumor cells through both mitogen-activated protein kinase kinase and phosphatidylinositol 3-kinase dependent pathways." (PMID 17498291, 2007). "Hepatocyte growth factor staining was more uniform within the SCLC tumour, with only slightly stronger staining along the invasive edge." (PMID 17667909, 2007). "Infusion of HGF increases blood flow and oxygenation in organs that have high levels of the HGF receptor and in smaller vessels in tumours, suggesting a potential use of functional molecular imaging in cancer." (PMID 17576468, 2007). "The Hepatocyte Growth Factor (HGF) receptor c-MET tyrosine kinase is expressed on epithelially derived tumour cells, and is involved in HGF mediated activation of both MMP2 and MT1-MMP." (PMID 16465195, 2006). "It is now clear that HGF exerts pleiotropic effects in a wide variety of tumour cells, where binding of HGF to its tyrosine kinase receptor c-Met promotes scattering, proliferation, angiogenesis, enhanced cell motility, invasion and metastasis." (PMID 15846300, 2005). "This study initially revealed that HGF expression appeared independently in tumour cells and/or stromal cells." (PMID 15083185, 2004). "To clarify the role of HGF/c-Met in NSCLCs, we undertook a clinical study of HGF and c-Met expression in relation to tumour growth and vascularity." (PMID 15083185, 2004). "The present study demonstrates that tumour–stromal interaction between tumour cell-derived c-Met and stromal cell-derived HGF affects tumour growth and the prognosis of NSCLC patients." (PMID 15083185, 2004). "With regard to HGF expression in the stromal cells of tumours, 14 carcinomas (15.9%) were stromal HGF-positive and 74 carcinomas (84.1%) were stromal HGF-negative." (PMID 15083185, 2004). "Of the 14 stromal HGF-positive tumours, 11 tumours (78.6%) had a high Ki-67 index, and 33 tumours (44.6%) among the 74 stromal HGF-negative tumours had a high Ki-67 index." (PMID 15083185, 2004). "In conclusion, the present study on NSCLCs has demonstrated that intratumoral c-Met and stromal HGF expression promote tumour growth." (PMID 15083185, 2004). "Some tumour cell-derived factors, such as interleukin-1, basic fibroblast growth factor, and tumour necrosis factor-α, are involved in the overexpression of HGF in stromal fibroblasts." (PMID 15083185, 2004). "Increased Met and HGF/SF expression occurs in many tumours and the HGF/Met autocrine signalling pathway possibly has an oncogenic role." (PMID 12402142, 2002). "When tumour cells were grown in collagen gels, HGF/SF induced irregular branching extensions of cell aggregates formed by five out of eight adenocarcinoma cell lines, but significant lumen morphogenesis was distinctly absent." (PMID 9649128, 1998). "The serum concentration of HGF reflected pathological features, including tumour size and lymph node or liver metastasis, and it showed an association with various preoperative nutritional parameters and the preoperative haemoglobin level." (PMID 9716026, 1998). "A wide range of HGF/SF levels were found for all tumour classes, some effusions containing high levels above 4 ng ml-1." (PMID 8562345, 1996). "It is concluded that tumours within the pleura and adjacent lung tissue are usually exposed to biologically significant levels of HGF/SF." (PMID 8562345, 1996).